MET (MET proto-oncogene, receptor tyrosine kinase)
Diseases named in the same sentence as MET in open-access papers (continued):
Sharing a sentence is not in itself a finding about the gene and the disease.
non-small cell lung carcinoma (continued). "Background and aims: The MET exon 14 skipping (METex14) is an oncogenic driver mutation that provides a therapeutic opportunity in non-small cell lung cancer (NSCLCs) patients." (PMID 36230737, 2022). "Further studies are necessary to clarify the role of KRAS mutations and MYC amplifications in MET-altered non-small-cell lung cancer." (PMID 30459450, 2019). "Patients with advanced-stage non-small-cell lung cancer are included in MET inhibitor clinical trials, when the tumor shows either an exon 14 skipping mutation or a MET high-level amplification, mostly defined as at least ten gene copies per cell." (PMID 30459450, 2019). "High levels of MET protein expression, seen in half of non-small cell lung cancer (NSCLC) cases, are associated with poor prognosis." (PMID 29050231, 2017). "Elevated HGF expression and c-MET amplification have been linked with acquired resistance to epidermal growth factor receptor tyrosine kinase inhibitors (EGFR TKIs) in patients with non-small cell lung cancer (NSCLC)." (PMID 27422720, 2016). "For example, mutations involving MET exon 14 occur in 4% of non-small-cell lung cancer." (PMID 40564049, 2025). "Mechanisms underlying primary and acquired resistance to MET tyrosine kinase inhibitors (TKIs) in managing non-small cell lung cancer remain unclear." (PMID 38758826, 2024). "Furthermore, patients with MET-mutated non-small cell lung cancer (NSCLC) treated with crizotinib responded extraordinarily well, with a CBR of 71% and an objective response in 62% of patients." (PMID 38779868, 2024). "In this article, we outline updates on the clinical development of savolitinib, a novel, reversible c-MET kinase inhibitor conditionally approved in China for treatment of advanced non-small cell lung cancer (NSCLC) patients harboring MET exon 14 skipping mutation (METex14)." (PMID 36551608, 2022). "Furthermore, dysregulation of the MET tyrosine kinase is associated with resistance to targeted therapies in cancer patients and frequently occurs in non-small cell lung cancer (NSCLC) patients with EGFR inhibitor resistance." (PMID 31948451, 2020). "MET amplification is associated with acquired resistance to first-generation epidermal growth factor receptor (EGFR)-tyrosine kinase inhibitors (TKIs) in treating non-small-cell lung cancer (NSCLC); however, the therapeutic strategy in these patients is undefined." (PMID 30791921, 2019). "For instance, reduced m6A levels enhances the therapeutic efficacy of crizotinib, an ALK/ROS1/c-MET kinase inhibitor, in the treatment of non-small cell lung cancer (NSCLC) with high c-MET expression." (PMID 40533443, 2025). "Mutations in SMARCA4 have been shown to co-exist with KRAS mutations but are mutually exclusive from common targetable non-small cell lung carcinoma (NSCLC) oncogenes, including EGFR, ALK, MET, ROS-1, and RET." (PMID 40406754, 2025). "In non-small cell lung cancer, for instance, EGFR-mutant tumors with MET amplification, HER2 mutations, or PIK3CA alterations frequently develop resistance to EGFR inhibitors." (PMID 40076838, 2025). "Recently, small molecule inhibitors targeting c-MET, such as capmatinib and tepotinib, have entered clinical trials and shown positive results in patients with non-small cell lung cancer." (PMID 40078386, 2025). "A case with somatic duplication of the MET gene region containing exons 3-5 and encoding the SEMA domain in metastatic non-small-cell lung cancer was published in 2020." (PMID 40564049, 2025). "Key gaps and needs in targeting KRAS/BRAF/MET and other genomic alterations in non-small-cell lung cancer." (PMID 39237103, 2025). "We cultured tumor cells derived from five patients with MET-amplified non-small cell lung cancer into in vitro patient-derived organoids (PDO) and experimentally assessed the resulting cell viability under different cytotoxic treatments." (PMID 41368576, 2025).
non-small cell lung carcinoma (continued). "Previous meta-analyses have shown that c-MET is a poor prognostic marker in head and neck squamous cell carcinoma and non-small cell lung cancer." (PMID 40078386, 2025). "The ALK/MET inhibitor crizotinib is a promising cancer therapy used primarily for the treatment of non-small cell lung cancer, and demonstrated cytotoxic effects on cervical cancer, ovarian cancer, and also chordoma cell." (PMID 41442054, 2025). "CAFs in non-small cell lung cancer promote resistance to osimertinib through MET, Akt, epithelial-to-mesenchymal transition, and stemness pathways." (PMID 40723172, 2025). "Significantly, dysregulation of c-MET in non-small cell lung cancer (NSCLC) not only facilitates tumor proliferation, angiogenesis, and metastasis, but also alters the immune microenvironment." (PMID 39201787, 2024). "In summary, the pivotal role of the HGF/MET pathway in promoting invasion and metastasis, angiogenesis, and immune evasion in non-small cell lung cancer (NSCLC) highlights its significance in the disease process." (PMID 39201787, 2024). "This case report highlights the sensitivity of a novel MET fusion to capmatinib and emphasizes the need for comprehensive panels in non-small cell lung cancer and molecular tumor board discussions with specialized centers when rare findings arise." (PMID 38832711, 2024). "This interaction is crucial for maintaining the MET-amplified non-small cell lung cancer (NSCLC) oncogenic phenotype." (PMID 39201787, 2024). "Analysis was performed with non-small cell lung cancer H1993 cells, which constitutively overexpress active MET." (PMID 36766826, 2023). "The role of c-MET as member of the receptor tyrosine kinase superfamily in the signaling pathway of non-small cell lung cancer (NSCLC) has been extensively described." (PMID 36253641, 2023). "Capmatinib is a kinase inhibitor used to treat non-small-cell lung cancer (NSCLC) with MET exon 14 skipping." (PMID 37631077, 2023). "Capmatinib and Tepotinib are two FDA-approved Tyrosine Kinase Inhibitors (TKIs) that are used to treat non-small cell lung cancer (NSCLC) patients with MET exon 14 skipping." (PMID 37174093, 2023). "The mechanism of drug resistance of first/second-generation EGFR-TKIs in non-small cell lung cancer (NSCLC) is a secondary gene mutation, such as TK domain mutation (T790M), MET amplification, and RAS mutation." (PMID 37730961, 2023). "In non-small-cell-lung cancer, MET amplification is thought to be responsible for resistance to targeted drugs in EGFR-mutation-positive patients, which results in malignant biological behavior of tumors, such as invasion, metastasis, escape from apoptosis." (PMID 35401204, 2022). "To further characterize the safety of tepotinib in patients with MET exon 14 skipping non-small cell lung cancer, we analyzed adverse events of clinical interest in the phase II VISION trial (N = 255)." (PMID 35466070, 2022). "Capmatinib, a highly selective MET inhibitor (INC280), has shown an overall response of 41% in non-small cell lung cancer patients harboring a METΔex14 mutation as compared with 29% in patients with MET amplification." (PMID 35875139, 2022). "MET (hepatocyte growth factor receptor) is a target in several cancers, including non-small cell lung cancer, gastrointestinal cancer, and hepatocellular carcinoma." (PMID 35328639, 2022). "c-Met has attracted attention as a promising target in various cancers, such as non-small-cell lung cancer with MET alteration, MET-amplified esogastric adenocarcinomas and c-Met-overactive colorectal cancer." (PMID 36551686, 2022).
non-small cell lung carcinoma (continued). "Non-small cell lung cancer (NSCLC) driven by MET exon 14 skipping (METex14) occurs in 3-4% of NSCLC cases and defines a subset of patients with distinct characteristics." (PMID 36338758, 2022). "Aberration of the HGF/c-MET system is well documented in several human cancers, such as non-small cell lung cancer (NSCLC), squamous cell carcinoma of the head and neck (HNSCC) cancer, as well as other carcinomas." (PMID 35807022, 2022). "It was approved by the FDA for patients with metastatic non-small cell lung cancer harboring MET exon 14 skippings based on the GEOMETRY mono-1 study in 2020." (PMID 36109787, 2022). "Recent research has shown that non-small-cell lung carcinomas with acquired resistance to EGFR inhibitors tend to show amplifications in MET." (PMID 35069735, 2022). "ATP-binding cassette subfamily B member 1 (ABCB1) is elevated in CSCs and contributes to MET inhibitor resistance in non-small cell lung cancer (NSCLC)." (PMID 36612059, 2022). "Tepotinib is a highly selective MET inhibitor approved for treatment of non-small cell lung cancer (NSCLC) harboring METex14 skipping alterations." (PMID 35771259, 2022). "Tepotinib is a highly selective, potent, mesenchymal–epithelial transition factor (MET) inhibitor, approved for the treatment of non-small cell lung cancer (NSCLC) harboring MET exon 14 skipping." (PMID 35385993, 2022). "In some cancers, such as gastric and non-small cell lung carcinomas (NSCLCs), hyperactivity of c-MET is the result of multiple copies of the MET gene and these cells seem to be largely dependent on sustained c-MET activity for their growth and survival." (PMID 33596971, 2021). "The KRAS mutation has been shown to be one of the resistant mechanisms in MET-mutant non-small cell lung cancer patients receiving the c-MET tyrosine kinase inhibitor." (PMID 34439385, 2021). "Exon skipping (ES) represents one of the most frequent AS events, and in non-small cell lung cancer (NSCLC) MET exon 14 skipping was shown to be targetable." (PMID 33921709, 2021). "MET-addicted non-small cell lung cancer (NSCLC) with high-level MET amplification and MET exon 14 alterations is known to be sensitive to treatment with crizotinib, while the presence of secondary MET mutations is described as a potential resistance mechanism." (PMID 34885165, 2021). "MET exon 14 skipping is an oncogenic driver occurring in 3–4% of non-small cell lung cancer (NSCLC)." (PMID 34037224, 2021). "MET amplification plays an important role in the development of non-small-cell lung cancer (NSCLC) either de novo or in resistance to epidermal growth factor receptor tyrosine–kinase inhibitor (EGFR-TKI) settings." (PMID 34758872, 2021). "In this review, we discuss the molecular epidemiology of the main druggable genetic alterations in non-small cell lung cancer, namely EGFR, KRAS, BRAF, MET, and HER2 mutations or amplification, as well as ALK and ROS1 fusions." (PMID 33435440, 2021). "Osimertinib is able to increase the phosphorylation of AXL in EGFR-mutated non-small cell lung cancer (NSCLC) cells, which subsequently activate HER3, MET, EGFR and the corresponding downstream signals." (PMID 32171304, 2020). "It has also been demonstrated that micro-RNA-499a-mediated suppression of non-small cell lung cancer cell migration and invasion occurs via downregulation of c-MET gene expression." (PMID 32679742, 2020). "One such agent, amivantamab, is a fully human anti-EGFR and c-MET-targeting antibody that demonstrated a 36% objective response rate and 10 month median response duration in patients with non-small cell lung cancers (NSCLC) harboring EGFR exon 20 insertions." (PMID 33364187, 2020). "Another example is MET, a well-known drug target in non-small-cell lung cancer, both protein overexpression and gene amplification of MET indicated a better response of patients to MET inhibitor treatment and worse prognosis." (PMID 33178818, 2020).
non-small cell lung carcinoma (continued). "Mesenchymal-epithelial transition factor (MET) gene is an important tumor driver gene of non-small cell lung cancer (NSCLC)." (PMID 32702795, 2020). "Li and colleagues focused on MET receptor, using various antibody fragments derived from an anti-MET antibody to obtain images of non-small-cell lung cancer xenografts from cell lines resistant to targeted anti-EGFR therapy due to the overexpression of MET." (PMID 31544839, 2019). "Especially for the MET, some researchers found that high MET gene copy number leads to shorter survival in patients with non-small cell lung cancer." (PMID 31888619, 2019). "Non-small-cell lung cancer driven by MET aberrations is currently considered as a heterogeneous group of tumors." (PMID 30459450, 2019). "In Non Small Cell Lung cancer ~5% of queried patients showed a MET gene alteration, 1.66% of which were MET amplification." (PMID 31613934, 2019). "Resistance to EGFR tyrosine kinase inhibitor (TKI) in non-small cell lung cancer (NSCLC) has been attributed to MET amplification." (PMID 31480591, 2019). "In particular, tyrosine kinase inhibitors targeting specific molecular alterations, among other MET, have greatly improved the prognosis of non-small-cell lung cancer patients." (PMID 30459450, 2019). "There are two Phase II trials underway: NCT03539536, “Study of Telisotuzumab Vedotin (ABBV-399) in Subjects with Previously Treated c-Met+ Non-Small Cell Lung Cancer” and NCT03574753, “Lung-MAP S1400K; c-MET Positive”." (PMID 31159276, 2019). "The MET proto-oncogene receptor tyrosine kinase and its ligand, the hepatocyte growth factor were first characterized in the mid-1980s and their involvement in non-small-cell lung cancer tumorigenesis was first described in the 1990s." (PMID 30459450, 2019). "This case suggests that crizotinib is effective against non-small cell lung cancer with MET exon 14 alterations." (PMID 31312453, 2019). "PAX8 is reported to be expressed in metastatic non-small cell lung cancers and to promote cell migration via interaction with MET and RON." (PMID 29535844, 2018). "The receptor tyrosine kinase, MET, is one of the most commonly dysregulated oncogenes in non-small cell lung cancer (NSCLC) and met gene amplification has been shown to be a major mechanism in which cancers develop resistance to EGFR inhibitors." (PMID 30249178, 2018). "In non-small cell lung cancers (NSCLC), mutations in NF1, MET, and ERBB2 account for up to 13% of tumors analyzed by molecular profiling, and elevation in MAPK and PI3K activity was observed in a large proportion of cases." (PMID 30359271, 2018). "In non-small cell lung cancer cells, MET overexpression increased EGFR downstream signaling and the combined use of dual EGFR/HER2 and MET tyrosine kinase inhibitors resulted in a maximal growth inhibition." (PMID 30227653, 2018). "MET amplification is actionable in non-small cell lung cancers and renal cell carcinoma (OncoKB level 2)." (PMID 30442178, 2018). "Overexpression of both HGF and/or its receptor c-MET have been reported in non-small cell lung cancer (NSCLC) cell lines and patients." (PMID 29069748, 2017). "c-MET is considered a promising oncogenic driver in non-small cell lung cancer (NSCLC) after the discovery of epidermal growth factor receptor (EGFR) and anaplastic lymphoma kinase (ALK)." (PMID 28442019, 2017). "In non-small cell lung cancer the results are inconsistent, however HGFR protein levels have been reported to be predictive for anti-MET treatment in clinical studies whereas these results were not confirmed in a phase III trial (METLung)." (PMID 27894094, 2017). "Because we have limited knowledge about the natural history of MET mutant tumors, the current study was aiming to determine the clinical and pathological characteristics in non-small cell lung cancers (NSCLC)." (PMID 27223439, 2016).
non-small cell lung carcinoma (continued). "In fact, acquired resistance to gefitinib, an EGFR tyrosine kinase inhibitor, can be mediated by MET amplification in patients with non-small cell lung cancer (NSCLC)." (PMID 27055285, 2016). "The two main mechanisms of resistance to EGFR tyrosine kinase inhibitors (TKIs) in non-small cell lung cancer (NSCLC) are the occurrence of T790M secondary mutation in the kinase domain of EGFR and MET amplification." (PMID 27726115, 2016). "This distinct pattern of increased MET activation near the invasive tumor front has been previously observed in non-small cell lung cancer and melanoma." (PMID 27655711, 2016). "miR-130a has been reported to reduce resistance to Gefitinib and TNF-related apoptosis-inducing ligand (TRAIL) in Non-small cell lung cancer by down-regulating MET and miRNA-221/222." (PMID 25890369, 2015). "Several inhibitors against MET are currently being evaluated in clinical trials with very promising preliminary results in non-small cell lung cancer and hepatocellular carcinoma." (PMID 25230070, 2014). "MET is overexpressed in various solid tumors (eg. small cell lung cancer, non-small cell lung cancer, gastric cancer, renal cell carcinoma, and breast cancer) and its overexpression is often associated with an aggressive phenotype and poor prognosis." (PMID 24465403, 2014). "In cancer, miR-130a targets MET in non-small cell lung carcinoma and can target ATG2B and DICER1 to kill Chronic Lymphocytic Leukemia cells." (PMID 24885472, 2014). "The understanding of the role of gene mutations (EGFR, K-RAS and MET), gene fusions (ALK) and rearrangements (ROS-1), has improved the management of non-small-cell lung cancer patients." (PMID 25149536, 2014). "The final results of a Phase II trial showed that patients with advanced non-small cell lung cancer bearing tumors with high MET expression (scored as “MET positive”) benefit from the combination of onartuzumab and erlotinib (an inhibitor of EGF receptors)." (PMID 28548076, 2014). "For instance, several MET inhibitors are already showing encouraging results in cancers such as hepatocellular carcinoma and non-small cell lung cancer [26–, 30]." (PMID 25230070, 2014). "In order to characterize c-MET levels in human tumors, we obtained 15 human Non-Small Cell Lung (NSCLC) cancer specimens." (PMID 21283737, 2011). "Together, our results suggest that MET-based targeted inhibition using small-molecule MET inhibitor can be a potential treatment strategy for T790M-EGFR-mediated erlotinib-resistant non-small-cell lung cancer." (PMID 19238632, 2008). "Furthermore, although c-MET-targeted therapies have shown promising results in other cancers, particularly non-small cell lung cancer, there remains a paucity of clinical trials and data on c-MET inhibitors in ESCC." (PMID 40078386, 2025). "Furthermore, the Exo-AAV platform supports conjugation with additional mAbs (e.g., targeting EGFR, Trop-2, NK-1R or MET), broadening its applicability to heterogeneous TNBCs and potentially other cancers, such as non-small cell lung cancer." (PMID 41462289, 2025). "Crizotinib, a tyrosine kinase inhibitor (TKI) targeting ALK, MET and ROS1, was approved as the first-line drug for ALK-rearranged metastatic non-small cell lung cancer, as ALK rearrangement is known as “diamond mutation” and lead to high sensitivity to ALK TKIs." (PMID 37733896, 2024). "Crizotinib, a small-molecule tyrosine kinase inhibitor targeting ALK, MET and ROS1, is the first-line drug for ALK-positive metastatic non-small cell lung cancer and is associated with severe, sometimes fatal, cases of cardiac failure, which increases the risk of mortality." (PMID 37733896, 2024). "Indeed, treatment modalities for patients with metastatic non-small cell lung cancer have changed since the US FDA approved c-MET inhibitors such as capmatinib (Tabrecta®) and tepotinib (Tepmetko®)." (PMID 38238761, 2024).